INS (insulin)
Diseases named in the same sentence as INS in open-access papers (continued):
Sharing a sentence is not in itself a finding about the gene and the disease.
diabetes (continued). "Moreover, ketogenic diets were indeed the principal therapeutic option for diabetes before the discovery of insulin in the early 20th century." (PMID 32640608, 2020). "Despite abundant evidence for the role of diabetes in the pathophysiology of atherosclerosis and clinical cardiovascular events, insights into the contribution of early disruptions in serum levels of insulin and glucose on the development of atherosclerosis remain scarce." (PMID 31958313, 2020). "Abnormalities in intestinal insulin signalling could be present in several diseases, including obesity, diabetes and cancer and could contribute to/prevent the comorbidities associated with these diseases." (PMID 31936857, 2020). "Prospective randomised clinical trials are needed to evaluate the effects of IL-6R inhibition on glycaemic indices, insulin sensitivity and pancreatic β cell function in patients with comorbid RA and diabetes and determine the clinical relevance of differences in IL-6R, IL-1β and TNF inhibition." (PMID 32907617, 2020). "Why some people have to take tablets as well as insulin to manage diabetes?" (PMID 32310150, 2020). "Clinical and laboratory data were obtained from the patients’ medical records, including age, sex, anthropometric measurements, duration of diabetes, daily insulin dose (IU), degree of metabolic control based on mean annual hemoglobin A1c (HbA1c) values, comorbidities and treatments." (PMID 31434460, 2020). "This study explains various mechanisms involved in the treatment of diabetes by using Viola odorata and explains that this plant enriches the identified target genes that are involved in the treatment of metabolic faults such as insulin resistance." (PMID 33490239, 2020). "2‐II‐1 also received treatment of insulin for diabetes, but she got poor blood glucose control." (PMID 33016646, 2020). "When I was hospitalized because of diabetes for insulin, that was the worst." (PMID 32013898, 2020). "Higher glycemia in animals with diabetes treated by HMB when compared with STZ-treated animals without HMB therapy is in favor of studies reporting that HMB decreases sensitivity to the effect of insulin." (PMID 33114049, 2020). "Furthermore, several studies have highlighted that SSRIs, which increase the level of endogenous serotonin, can improve glucose tolerance and insulin sensitivity in diabetes both experimentally and clinically." (PMID 33384599, 2020). "Previously, metformin rather sulfonylurea or insulin had been shown benefits in T2DM patients in the United Kingdom Prospective Diabetes Study (UKPDS) in decreased risks of macrovascular complications and all-cause mortality that persisted after trial was over." (PMID 33167990, 2020). "And insulin has a direct vasodilating effect, and the average vasodilatory response was in the range 15–30% under the physiological dose, but this effect was weakened in patients with IR or diabetes." (PMID 32811450, 2020). "Recent studies indicated that this chronic ER stress may be involved in the β cell degeneration during the late phases of diabetes and the gradual decrease of insulin secretion capacity of the pancreas." (PMID 32256145, 2020). "Previous studies have shown the involvement of IGF2BP2 gene polymorphism in attenuating the first phase of glucose-stimulated insulin secretion based on hyperglycaemic clamps, and the regulation of pancreatic β-cell function in Type 2 diabetes mellitus (T2DM) patients." (PMID 32662505, 2020). "A multipronged approach is required to manage diabetes and reduce the severity of complications and our simple interventions include food diaries and physical activity logs together with managing blood sugar by insulin therapy." (PMID 32312302, 2020). "Rezania and colleagues developed a 7-step protocol that converts hESCs into insulin-producing cells (IPCs) that could reverse diabetes in mice 40 days after transplantation." (PMID 32880857, 2020).
diabetes (continued). "Our study suggests that PGRMC1 may be an emerging target for controlling gluconeogenesis and diabetes in an insulin-resistant state." (PMID 33005004, 2020). "Overall, the downregulated beta cell mass, proliferation and absolute insulin secretion with AGI treatment may be beneficial to beta cell preserve in diabetes and may also require FXR signalling." (PMID 32034442, 2020). "For example, a 63-year-old woman with diabetes said: “I cannot do all that they say to do, to check my ulcers in the foot, to walk, to maintain insulin levels, to eat my food, how to eat, what to eat, to check my sugar level several times a day, to take tests, to visit my doctor..." (PMID 33072199, 2020). "We also intend to explore whether the chronic administration of ghrelin has any role in the augmentation of pancreatic beta cell number or the prevention of diabetes mellitus, using a rodent model of diabetes where insulin is severely depleted." (PMID 32325912, 2020). "FPG is the most commonly used indicator of diabetes, representing the secretion of basal insulin." (PMID 33332396, 2020). "GEMINI found that patients treated with carvedilol had lower HbA1c and improved insulin sensitivity compared to those treated with metoprolol (Bakris, Fonseca, & Katholi, 2004), along with an improvement in patients own perceptions of diabetes‐related symptoms." (PMID 32170823, 2020). "Diabetes is a metabolic disease caused by lack of insulin secretion, insulin action or insulin resistance, which impairs the body’s ability to process blood glucose." (PMID 32313785, 2020). "In addition, two patients had diabetes mellitus (DM), and one patient was treated with insulin therapy." (PMID 33092145, 2020). "€3229.75 total costs were reported for 6 months before and after insulin initiation, including €1366.39 for diabetes-related hospitalisations, €709.29 for physician consultations, €476.81 for oral antidiabetics and €250.27 for insulin as well as €315.50 for blood glucose monitoring." (PMID 33198734, 2020). "Intensive insulin therapy in the early stages of diabetes has resulted in remission." (PMID 32597475, 2020). "Our findings show the potential role of 30 min and 1-h post-load glucose and 2-h insulin levels as risk factors for retinopathy lesions among the participants without previously diagnosed diabetes or hypertensive medication." (PMID 33091029, 2020). "A prevailing hypothesis in the field of diabetes is that if a cell is bathed in excessive glucose, it ought to take up more glucose, especially if the cell expresses non-insulin dependent glucose transporters, such GLUT1." (PMID 32118048, 2020). "Insulin sensitivity is one of the predictors of diabetes, therefore, these findings indicated that carriers of rs7403531 may be predisposed to T2D by decreasing insulin sensitivity." (PMID 32260174, 2020). "As GLUT4 is the main glucose transporter in skeletal muscle, it remains to be established whether an impaired DHA transport into skeletal muscle in insulin resistance may contribute to the tissue-specific pathology of diabetes." (PMID 32591906, 2020). "The study aims to investigate the association of two PAT-derived endothelial function parameters reactive hyperemia index (RHI) and mean baseline amplitude (MBA) with follow-up glucose and insulin parameters and the development of (pre)diabetes and type 2 diabetes." (PMID 32690629, 2020). "The mechanisms for insulin resistance have been extensively reviewed by Petersen and Shulman (2018); multiple MRS studies have revealed that the rate-controlling step for insulin-stimulated glycogen muscle synthesis in those with diabetes or insulin resistance is glucose transport." (PMID 32903666, 2020). "The same pathogenesis is suggested regarding insulin function in type 2 diabetes mellitus." (PMID 32095207, 2020). "The difference could also be a result of the insulin resistance as an incipient phase of type 2 diabetes mellitus." (PMID 32512870, 2020).
diabetes (continued). "Improvements in lipid parameters and blood pressure, as well as improvement of fasting glucose, insulin levels, and reduced progression to type 2 diabetes mellitus were seen in the clinical studies.41, –43 A specific cardiovascular safety trial has not been conducted to date." (PMID 32030121, 2020). "In our Spanish cohort, characteristics related with type 2 diabetes, such as longer diabetes duration, need for insulin therapy and higher baseline HbA1c values, were strongly associated with all assessed outcomes (remission, good metabolic control, time-within-remission range and recurrence)." (PMID 32283783, 2020). "Another explanation for these findings may be the use of insulin in diabetes patients during leukemia treatment." (PMID 33437503, 2020). "Low protein models of fetal programming have observed that young offspring who are predisposed to diabetes with aging have reduced insulin secretion but only slight or no changes were observed in glucose intolerance." (PMID 32315370, 2020). "DA group showed increase in insulin levels compared with the group of diabetes." (PMID 33203103, 2020). "In 1922, insulin was first successfully isolated by a team of Canadian scientists in Toronto; a discovery that brought about a true medical success and a milestone in the history of treating diabetes." (PMID 33066443, 2020). "Since both amylin and H2S are involved in regulating the insulin release; therefore, there is a possibility that there may be an interaction between amylin and H2S in diabetes mellitus." (PMID 32436936, 2020). "Insulin can generally rapidly lower blood glucose and additionally protects against the many adverse consequences of hyperglycemia in a range of disorders unrelated to diabetes." (PMID 33167495, 2020). "First, whether decreased OGN levels can restore primary cilia integrity and insulin sensitivity in cases obesity/diabetes." (PMID 33139642, 2020). "Diabetes is a chronic disease that occurs either when the pancreas does not produce enough insulin (type 1 diabetes) or when the body cannot effectively use the insulin it produces (type 2 diabetes)." (PMID 32012794, 2020). "Type 2 diabetes mellitus, accounting for approximately 90% of all diabetes mellitus cases, is hallmarked by insulin resistance, a pathological phenomenon where cells fail to respond to insulin to increase glucose uptake and utilization." (PMID 33101209, 2020). "Lack of insulin production (Type 1 diabetes, T1D) or lack of insulin responsiveness (Type 2 diabetes, T2D) causes systemic metabolic changes such as hyperglycemia (HG) which contribute to the pathology of diabetes." (PMID 32582175, 2020). "Poor compliance with or no insulin regimen were directly associated with severity of diabetic ketoacidosis in T1D patients in Pakistan, who needed longer hospital stays." (PMID 32312302, 2020). "The Nrf2/Keap1/ARE signaling pathway is the primary transcriptional regulator of intracellular redox, and, in a mouse model of diabetes, induction of Nrf2 overexpression either by genetic Keap1 knockdown or by pharmacological means can enhance sensitivity to insulin and improve disease symptoms." (PMID 33167495, 2020). "T2D patients (known diabetes duration: 2.5 [0.1; 5.0] years) had 43%, 44%, and 63% lower muscle insulin sensitivity (IS), metabolic flexibility (P < 0.01) and AT IS (P < 0.05), 73% and 31% higher HCL (P < 0.05), and DSAT-thickness (P < 0.001), but similar hepatic IS compared with CON." (PMID 31838512, 2020). "Moreover, in people with diabetes, regular PA potentially reduces the amount and dose of antidiabetic therapy and insulin dosage." (PMID 33467285, 2020). "It has been discovered through epidemiological studies that there is a relationship between type II diabetes (NIDDM), human insulin- or insulin analog-based diabetes treatment, and the development of some cancers such as breast, pancreas, colon, and rectum, as well as kidney." (PMID 31978979, 2020).
diabetes (continued). "This study aimed to evaluate the characteristics of total bilirubin (TBIL), direct bilirubin (DBIL), and indirect bilirubin (IBIL) and their relationships with insulin sensitivity in obese patients with impaired glucose regulation and type 2 diabetes mellitus (IGR/T2DM) in China." (PMID 32802055, 2020). "When patients with suboptimally-controlled diabetes switched from prior anti-hyperglycemic regimens to basal-bolus insulin therapy using V-Go, there was a statistically significant reduction in A1C as well as a significant improvement in patients achieving an A1C goal of < 8%." (PMID 33202616, 2020). "Of these, 1311 (57.4%) was only on oral anti-diabetes drugs, and 726 (31.8%) had insulin treatment." (PMID 32646432, 2020). "At the same time, the administration of antioxidants has been reported to usually attenuate diabetes-associated pathological changes in cells, but not always affect glucose levels and insulin sensitivity of the organism (see review)." (PMID 32911736, 2020). "According to the studies in Ethiopia poor glycemic control was associated with higher body weight, knowledge deficit about diabetes, poor self-care practice, being on insulin therapy, longer duration of diabetes, poor adherence to medication and their educational status." (PMID 32528672, 2020). "First, insulin pumps are prescribed in tertiary centers by qualified diabetes teams." (PMID 33334003, 2020). "The possible role of insulin clearance in pathogenesis of Type 2 diabetes began with a hypothesis (lower clearance predicted diabetes) and examined with population studies (lower clearance in African American adults and children)." (PMID 33658981, 2020). "The beneficial effects of C-peptide against pathologies induced by diabetes, may be an advantages in replacement therapies together with insulin treatment for both types of diabetes." (PMID 31963760, 2020). "The counselling sessions could cover education on chronic diseases, training on insulin injection for diabetes patients, taking and tracking of blood pressure and blood sugar readings, as well as guidelines on lifestyle practices." (PMID 32106838, 2020). "Combined, it might suggest that East Asians, with low endogenous capacity for insulin secretion, cannot compensate for increased insulin requirements with aging and thus develop diabetes at a younger age." (PMID 32630741, 2020). "Global and pancreas-specific overexpression of let-7 results in impaired glucose tolerance, while let-7 inhibition leads to an insulin-sensitized state that can resist high fat diet-induced diabetes, and it is sufficient in this case to treat glucose tolerance impairment." (PMID 31940853, 2020). "Similarly, in rabbit and dog models of diabetes mellitus, a mild prolongation of repolarization and a decreased repolarization reserve due to downregulation of IKs and Ito (reversible by insulin treatment) were observed." (PMID 32581808, 2020). "On the other hand, decreased pCREB is identified as one of the main reasons for cognitive decline in diabetes, maybe through decreased insulin levels." (PMID 32405353, 2020). "On the other hand, EVs isolated from insulin resistant adipocytes (HGHI) showed proteins implicated in diabetes pathways, that were not present on EVs secreted by lipid hypertrophied cells." (PMID 32214011, 2020). "Recently, Moulton and colleagues conducted a meta-analysis of 19 published RCTs (five of metformin, two of peroxisome proliferator-activated receptor (PPAR)-γ receptor agonists, two of incretin-based therapies, and one of insulin) on the effects of diabetes treatments on depressive symptoms." (PMID 32971941, 2020). "Interestingly, normalisation of glucose levels using insulin restores the incretin properties of GIP in diabetes." (PMID 32436022, 2020).
diabetes (continued). "Type 1 diabetes mellitus (T1DM) is the most common chronic autoimmune disease in young patients and is characterized by the loss of pancreatic β cells; as a result, the body becomes insulin deficient and hyperglycemic." (PMID 32641151, 2020). "Type 2 Diabetes Mellitus (T2DM), one of the most common metabolic disorders, is caused by a combination of two primary factors: defective insulin secretion by pancreatic β-cells and the inability of insulin-sensitive tissues to respond appropriately to insulin." (PMID 32872570, 2020). "When compared with all patients not receiving insulin, insulin use in patients without diabetes was associated with a higher rate of death or major complication (adjusted odds ratio [OR]=1.54; 95% confidence interval [CI] 1.15-2.04; P=0.003)." (PMID 33118731, 2020). "Clinical trials revealed that SGLT2i could improve glycemic control and reduced the dosage of insulin, even in subjects with type 1 diabetes mellitus (T1DM)." (PMID 33362717, 2020). "In STZ-induced diabetes, insulin drop caused the failure of lipoprotein lipase to perform normal physiological functions, which leads to hyperlipidemia and hypercholesterolemia." (PMID 32967670, 2020). "Although requiring further confirmation to provide that our platform is suitable to detect glycemic fluctuation (minutes/hour), the present data indicate that our novel noninvasive approach to diabetes monitoring has the potential to provide discrimination of short-time insulin treatment." (PMID 32182246, 2020). "Younger patients with non-insulin-treated diabetes mellitus and CAD of limited extent may be the most suitable candidates for treatment with EE-BRS (as an alternative to EES), as they might have the greatest benefit from the bioresorbable nature of the device." (PMID 33008407, 2020). "Moreover, in addition to its therapeutic application in diabetes, insulin therapy can improve lipid metabolism and decrease mortality for myocardial infarction patients." (PMID 32506749, 2020). "Later it was shown in animal model that in rats with streptozotocin-induced diabetes DDW decreased blood sugar if the animals simultaneously received insulin (two other indicators of diabetes, HbA1C and fructosamine were also significantly lowered in these rats)." (PMID 32197347, 2020). "SMBG is an invaluable method for monitoring glycemic status; current guidelines recommend its use in all patients with T1D, type 2 diabetes mellitus (T2DM), or any other forms of diabetes (e.g., gestational diabetes) that require administering multiple subcutaneous insulin injections." (PMID 32312302, 2020). "Finally, these findings will enable to identify potential between the action of natural and conventional therapy and insulin and explore possible avenues to bypass or overcome diabetes." (PMID 33256066, 2020). "Akt levels themselves were not appreciably altered in the KO, but Akt phosphorylation was strongly inhibited in Tm7sf2-KO liver, indicating a possible defective insulin signaling that could lead to obesity and diabetes." (PMID 33330474, 2020). "To date, to the best of our knowledge, there has been no study on a national or international level to evaluate the knowledge and attitude regarding insulin pumps in physicians of different specialties who may provide care to adults and children with diabetes." (PMID 33334003, 2020). "Metformin and insulin are standard drugs for the treatment of diabetes." (PMID 32156062, 2020). "Criteria for diabetes progression after the onset of disease are mainly related to antidiabetic drug requirement (oral hypoglycaemic agents (OHA)s or insulin requirement), drug failure, drug addition, increasing drug dosage, glycaemic level measured as HbA1c, and decline in beta‐cell function." (PMID 32318630, 2020). "Insulin was immediately prescribed in the 4 women with overt Diabetes Mellitus." (PMID 32734411, 2020).